BMP2 (bone morphogenetic protein 2)
Diseases named in the same sentence as BMP2 in open-access papers (continued):
Sharing a sentence is not in itself a finding about the gene and the disease.
periodontitis (22 papers, 2019 to 2026). An acute or chronic inflammatory process that affects the tissues that surround and support the teeth. "A separate study found that Vit D supplementation of Vit D-insufficient diabetic periodontitis patients resulted in elevated BMP-2 serum and gingival crevicular fluid samples." (PMID 41148797, 2025). "In a rat model of periodontitis, cocoa pod husk extract increased alveolar bone regeneration by enhancing osteoblast numbers and bone morphogenetic protein-2 (BMP-2) expression." (PMID 39594518, 2024). "More interestingly, some of these key genes also play a role in the pathology of peri-implantitis, such as WNT3A, PI3K, BMP2, which indicated the interaction between periodontitis and peri-implantitis." (PMID 35491409, 2022). "One way ANOVA test results of the effect of gingival BMP2 levels on the severity of periodontitis in acromegaly patients and the healthy controls." (PMID 33421969, 2021). "As the local gingival BMP2 levels increased, periodontitis severity decreased in the acromegaly patients." (PMID 33421969, 2021). "In vivo, the exclusive reliance on a rat periodontitis model lacks representativeness, and the restricted focus on two inflammation-associated cytokines (TNF-α and IL-1β) overlooks other critical mediators (e.g. IL-6) and bone formation markers (e.g. BMP-2, OCN)." (PMID 40958806, 2025). "This study evaluated the therapeutic potential of curcumin by examining its effects on two markers of periodontal health, BMP-2 and OPN, within an inflammatory environment induced by LPS to simulate periodontitis." (PMID 39897215, 2025). "Meanwhile, DUBs, including OTUD1, A20, CYLD, UCH‐L1 and USPs, also broadly modulate periodontitis progression by regulating signalling pathways such as NF‐κB, Wnt/β‐catenin, NLRP3, and BMP2." (PMID 39626954, 2025). "The differential gene heatmap and volcano plot showed that compared with the healthy group, osteogenesis-related genes, such as RUNX2, BMP2, and COL1, in the periodontitis group decreased significantly." (PMID 38474198, 2024). "This resulted in a milieu with limited amounts of inflammatory cytokines and reparative cytokines including bone morphogenetic protein-2 (BMP-2), which stimulated PDLC development, periodontal tissue regeneration, and the arrest of periodontitis progression." (PMID 37605182, 2023). "The further PPI analysis has revealed some of genes play a key role in pathogenesis in periodontitis, including WNT3A, BMP2, CXCL12 and PI3KR2." (PMID 35491409, 2022). "This created a microenvironment with low levels of inflammatory cytokines and high levels of reparative cytokines like bone morphogenetic protein-2 (BMP-2), which led to PDLC differentiation, periodontal tissue regeneration, and stopping the progression of periodontitis." (PMID 38183090, 2024). "When those with and without chronic periodontitis were subgrouped, gingival BMP-2 levels were statistically lower in those participants with chronic periodontitis then those without periodontitis (29.4 ± 11.2 vs. 41.2 ± 23.2, respectively, p = 0.027)." (PMID 33421969, 2021). "When the acromegalics and healthy controls with and without chronic periodontitis were analysed separately, both the acromegalics and the healthy control group, revealed similar gingival BMP-2 and BMP-4 levels." (PMID 33421969, 2021). "For all the participants, gingival BMP-2 levels were statistically lower in those participants with chronic periodontitis then those without periodontitis (29.4 ± 11.2 vs. 41.2 ± 23.2, respectively, p = 0.027)." (PMID 33421969, 2021). "In addition, AuNPs could regulate the macrophage phenotype to produce a microenvironment with restricted inflammatory cytokine levels and repair cytokines, such as bone morphogenetic protein 2 (BMP-2), thereby promoting periodontal tissue regeneration and preventing the progression of periodontitis." (PMID 34819109, 2021).
periodontitis (continued). "Gingival BMP-2 and BMP-4 levels were similar in acromegaly and control groups in general, with and without chronic periodontitis." (PMID 33421969, 2021).
hepatocellular carcinoma (20 papers, 2009 to 2025). A malignant tumor that arises from hepatocytes. "The relationship between BMP2 and hsa-miR-129-5p has been reported in many diseases, such as hepatocellular carcinoma and intervertebral disc degeneration." (PMID 35601497, 2022). "Next, we tested the active fraction for effect on a BMP2-induced SMAD1/5-dependent transcriptional reporter (BRE-luc) assay in HepG2 hepatocellular carcinoma cells." (PMID 32820031, 2020). "Treatment of hepatoma cells with BMP2 induced DGAT2 expression and activity via intracellular SMAD signaling." (PMID 32561790, 2020). "At a mechanistic level using gene-expression arrays, we found that ATIII treatment down-regulated multiple host cell signal transduction factors involved in the pathogenesis of cirrhosis and hepatocellular carcinoma, including Jun, Myc and BMP2." (PMID 23031791, 2012). "It binds to bone morphogenetic protein 2 (BMP-2) in hepatocellular carcinoma cells, and BMP-2 may simultaneously regulate both osteoclasts and osteoblasts." (PMID 41282615, 2025). "Even though several other BMPs, including BMP2, 4, 5, 7 and 9, all robustly induce hepcidin expression in primary hepatocytes or hepatoma cell lines, and their mRNAs are also detected predominantly in the NPCs of rat liver, they cannot compensate the function of BMP6 in Bmp6-/- mice." (PMID 23565256, 2013). "Thus, the induction of hepcidin by IL-6 and BMP-2 in the two hepatoma cell lines was reproducible, dose-dependent and mediated by the proximal promoter region, in agreement with previous studies." (PMID 19924283, 2009). "To confirm that the hepatoma cells responded to other known stimuli as previously reported and that the cloned hepcidin promoter fragments were functional, we stimulated HepG2 and Huh7 cells with IL-6 and BMP-2." (PMID 19924283, 2009). "As expected, BMP6 and BMP2 treatment, alone or in combination, induced HAMP mRNA in human Huh7 hepatoma cells." (PMID 36982241, 2023). "TANs secreted a large amount of bone morphogenic protein (BMP)-2 and TGF-β2 to elicit microRNA (miR)-301-3p expression in human hepatocellular carcinoma (HCC) cells." (PMID 32422991, 2020). "Treatment of hepatoma cells with BMP2 induces the expression and activity of DGAT2 (the gene involved in triglyceride synthesis) through intracellular SMAD signaling, suggesting a potential role for BMP2 in hepatic lipid metabolism." (PMID 40243151, 2025). "For example, a direct cross talk between Smad3 and STAT3 is bridged by p300 in hepatoma cells, a synergistic action of LIF-induced-Smad1 and BMP2-induced-STAT3 is bridged by p300 in neural cells, and Smad2/3 and STAT3 cooperatively interact in Th17 cell differentiation." (PMID 29963056, 2018). "The effects of Bone morphogenetic protein 2 (BMP-2) on the angiogenesis of hepatocellular carcinoma have not yet been observed and its molecular mechanisms is not clear." (PMID 27886213, 2016). "BMP2 and BMP6 regulate hepatocellular carcinoma progression and prognosis." (PMID 26029998, 2015). "BMP-2,-4, and -6 expression patterns in HepG2 and Huh7 cells could not explain the difference between the two hepatoma cell lines." (PMID 19924283, 2009).
Hyperglycemia (17 papers, 2015 to 2025). An increased concentration of glucose in the blood. "Elevated hyperglycaemia enhances the BMP-2/Msx2-Wnt pathway, causing some myofibroblasts to become osteogenic, while BMP-2 inhibition prevents arterial calcification." (PMID 39026232, 2024). "The expression of Tbx20 and Bmp2 also increased with concomitant increase in cardiomyocyte proliferation upon induction of hyperglycemia." (PMID 36805334, 2023). "We have also reported an increase in the activity of Tbx20 and Bmp2 during hyperglycemia in vitro and diabetic cardiomyopathy in vivo with concomitant increase in cardiomyocyte proliferation." (PMID 36805334, 2023). "An in-vitro study has reported that hyperglycemia results in reduced levels of BMP-2 in the bone mesenchymal stem cells." (PMID 35928902, 2022). "Previous in-vitro studies indicate that hyperglycemia reduces BMP-2 levels in bone mesenchymal stem cells and increases sclerostin levels in murine cell lines." (PMID 35928902, 2022). "Hyperglycemia also modulates some important bone turnover biomarkers such as bone morphogenetic protein-2 (BMP-2), which promotes osteoblast differentiation, and sclerostin, which retard bone formation." (PMID 35928902, 2022). "Hyperglycemia and diabetes are strong activators of BMP signaling, and BMP2 and BMP4 are associated with atherogenesis in hyperglycemia." (PMID 31561501, 2019). "Both BMP2 and BMP4 are upregulated in atherosclerotic lesions associated with oxidative stress, inflammation and hyperglycemia." (PMID 31561501, 2019). "Our previous studies established the involvement of the BMP2 signaling system in mediating retinal endothelial cell dysfunction under hyperglycemia and consistent with other studies which demonstrated the presence of a similar cross-talk between VEGF and BMP2 in HRECs." (PMID 33919531, 2021). "We also tested the effect of hyperglycemia on various components of BMP2 signaling pathway." (PMID 33584642, 2020). "In addition, to the observed in vivo increase in BMP2 by hyperglycemia, treatment of HRECs with HG upregulated mRNA of BMP2 and BMP4 and their downstream effectors such as ALKs, SMADs, and TGFβ mimicking the effect of rhBMP2 treatment." (PMID 33584642, 2020). "Moreover, plasma BMP2 levels positively correlate with calcium density of the plaque in hyperglycemia-induced vascular calcification." (PMID 31561501, 2019). "Hyperglycemia and insulin resistance directly decrease osteoblast differentiation and activity by decreasing the expression of osteoblast-related markers, including the Runt-related transcription factor 2 (Runx-2), osteocalcin, bone morphogenetic protein-2 (BMP-2), osteopontin." (PMID 34121973, 2021). "BMP2 is upregulated by hyperglycaemia, activating the ligand high mobility group box 1 (HMGB1), which translocates to the nucleus, binding to a cAMP response element (CRE) region of the BMP2 promoter, inducing its expression." (PMID 30619890, 2018).
myeloma (17 papers, 2005 to 2025). "This same study further showed that PRAL potentiates the anti-multiple myeloma effects of bortezomib by sponging miR-210 and inhibiting its ability to repress expression of bone morphogenetic protein 2 (BMP2)." (PMID 39966556, 2025). "This appears to be counterproductive, as BMP6 can more strongly induce apoptosis in primary myeloma cells via the type I receptor ACVRI (ALK2) as BMP2 and -4 can do via the BMPRIA and/or -IB." (PMID 28489849, 2017). "Consistently, neither the known inhibitor of apoptotic cell death zVAD-fmk nor the necroptosis inhibitor necrostatin-1 was able to rescue myeloma cell growth in the presence of BMP2." (PMID 29028819, 2017). "BMP2 induces apoptosis in myeloma cells and, remarkably, it was previously shown by Hallahan and colleagues that both, recombinant BMP2 treatment and enforced BMP2 expression following retinoid treatment, can induce apoptosis in medulloblastoma cells." (PMID 24252778, 2013). "Similar effects as demonstrated for BMP-6 on human B cells in the present study, were demonstrated for BMP-2, 4, 6 and -7 in human myeloma cells." (PMID 15877825, 2005). "In addition to the indirect effect via the microenvironment, we also investigated the direct anti-myeloma potential of BMP2 and BMP6." (PMID 41463400, 2025). "This conclusion is further corroborated by a direct comparison of BMP2 with FasL, an approved factor robustly triggering programmed cell death in the myeloma cell lines highlighting the differences in the effects induced by an apoptotic factor and those observed with BMP2." (PMID 29028819, 2017). "In addition, the inhibitory effect of BMP2 on the proliferation of the murine myeloma B cell line MPC-11 was determined by analysing incorporation of [3H]-thymidine into DNA." (PMID 29028819, 2017). "Inhibition of the proteasome system stimulated osteoblastogenesis and bone formation in calvariae in mice and in multiple myeloma patients, at least in part through the stimulation of bone morphogenetic protein-2 (BMP-2) gene expression and the inhibition of Runx2 proteolytic degradation." (PMID 28946669, 2017). "Interestingly, BMP2 was recently postulated to have a role in upregulating hepcidin expression in multiple myeloma." (PMID 23029472, 2012). "Furthermore, BMP-2, -4, 6 and -7 had an antiproliferative and a proapoptotic effect on multiple myeloma cells." (PMID 15877825, 2005). "In addition, HGF inhibits BMP-2-induced generation of osteoblasts in multiple myeloma, prompting the continued proliferation of MSCs and thus could promote chondroblast proliferation and cartilage formation in conjunction with BMP-4." (PMID 26098852, 2015). "Furthermore, BMP-2 has been shown to induce activation of STAT3 in myeloma cells." (PMID 15877825, 2005). "These cells responded poorly to the ligands BMP2, BMP4 and BMP10, that normally would require ALK3 to signal in myeloma cells." (PMID 36717825, 2023). "Most surprisingly we identified here a switch in ligand specificity as BMP2, BMP4, and BMP10, ligands that usually signal via ALK3 in myeloma cells, gained the ability to signal via ALK2 in the presence of FK506." (PMID 36717825, 2023). "Thus, in addition to osteogenic differentiation and disrupting stromal support for MM, BMP2 and BMP6 exert direct anti-myeloma effects and inhibit IL6-mediated proliferation." (PMID 41463400, 2025). "Given the key role of IL6 in supporting MM survival and proliferation, and our observation that BMP2 and BMP6 reduced IL6 expression in MSCs, we next assessed whether they could directly counteract IL6-induced myeloma growth." (PMID 41463400, 2025). "In patients with multiple myeloma, BMP-2, rather than IL-6, has been suggested as the major inducer of hepcidin, with BMP-2 levels inversely correlated with Hb levels." (PMID 37208766, 2023). "Ligands that typically signal via ALK3 in myeloma cells, BMP2, BMP4, and BMP10, did not induce apoptosis in cells lacking ALK3." (PMID 36717825, 2023).
myeloma (continued). "Furthermore, ACVR1/ALK2 is -in contrast to BMPRIA and -IB- ubiquitously expressed in myeloma cells, which potentially renders BMP6 a more versatile Activin A antagonist than BMP2." (PMID 28489849, 2017). "BMP-6 and BMP-9 signals through the type 1 receptor ALK2 in myeloma cells, whereas BMP-2 and BMP-4 do not signal in cells that express ALK2, but lack ALK3 and ALK6, as is the case for the INA-6 myeloma cell line." (PMID 26047946, 2015). "Using myeloma cell lines as a model system, we show that activin A antagonizes BMP-6 or BMP-9-signaling through ACVR2A/ACVR2B/ALK2, but not BMP-2 or BMP-4-signaling through BMPR2/ALK3 or BMPR2/ALK6." (PMID 26047946, 2015). "The main finding reported here is that activin A, by sharing receptors with BMP-6 and BMP-9, but not BMP-2 and BMP-4, may inhibit BMP-6 and BMP-9-induced apoptosis in myeloma cells." (PMID 26047946, 2015).
myopia (17 papers, 2008 to 2025). "The human BMP2 single nucleotide polymorphism (SNP) rs235770 is associated with myopia in multi-ethnic cohorts." (PMID 35833708, 2022). "Our study demonstrates that high myopia caused by Lrp2 insufficiency is prevented by targeting the downstream effector Bmp2." (PMID 35833708, 2022). "In this way, as this alteration occurred following significant structural change, the retinal level of BMP2 is likely associated with ocular growth and the development of myopia." (PMID 33671267, 2021). "For example, the gene BMP2 that Zhang, Liu & Wildsoet (2012) reported as mainly localised in the retina of chick, has previously been identified as a potential risk factor for myopia in chick retina/RPE and in chick RPE (Zhang, Liu & Wildsoet, 2012)." (PMID 29967729, 2018). "Furthermore, the Lrp2 knockout phenotype was rescued by RPE-specific overexpression of bone morphogenetic protein 2 (Bmp2), a gene associated with myopia in humans." (PMID 38635876, 2024). "Nonetheless, the effect of BMP2 alleles on controlling myopia is still unknown and to be able to explore its underlying mechanisms, further research will be required." (PMID 33671267, 2021). "The T allele, the one with the lowest frequency of the rs235770 polymorphism of the BMP2 gene, could have a significant effect on the response for the myopia control treatment." (PMID 33671267, 2021). "BMP2 was the only single gene from our study to fall near myopia-associated SNPs." (PMID 27625591, 2016). "At the BMP2 myopia locus, we observed a large difference in allele frequency between those of European and Asian ancestry, which may explain the difference in effect direction." (PMID 25241763, 2014). "In this study, we found that vitreous cavity injection of rBMP2 delayed the growth of myopia refraction and Axial length, and further explored the possible molecular mechanisms through the BMP2/Smad signaling pathway." (PMID 40375931, 2025). "By comparing the myopic eyes and the control eyes of the guinea pigs, the expression of BMP-2 and BMP-5 decreased in the myopic eyes, suggesting that they were associated with scleral remodeling during the myopia induction." (PMID 40696418, 2025). "As reported in our previous RNA sequencing study, Id3 gene expression was found to be downregulated across the CL wearing (myopia-inducing) period, i.e., after both one day and one week of CL wear, and consistent with the pattern of downregulation for Bmp2." (PMID 37759773, 2023). "This suggests that BMP2 is possibly functioning as a modulator for inflammation rather than influencing the growth signal in the development of myopia." (PMID 29967729, 2018). "BMP2 gene expression in chick RPE is regulated by a defocus signal, and in form-deprivation myopia, BMP-2 expression is reduced in the posterior sclera, but the BM2 gene expression in choroid of tree shrew is up-regulated during LIM." (PMID 25965995, 2015). "From this study, we concluded that BMP-2 is involved in scleral remodeling in the development and recovery of lens-induced myopia." (PMID 25965995, 2015). "In particular, the study aimed to characterize the changes in BMP-2 expression in the sclera in a mammalian model of lens-induced myopia and recovery from myopia and to investigate the capacity of BMP-2 to regulate ECM production in fibroblasts in vitro." (PMID 25965995, 2015). "This study showed that BMP-2 was down-regulated in the sclera of lens-induced myopia guinea pig and that BMP-2 promoted the synthesis of ECM in HSFs in vitro." (PMID 25965995, 2015). "In the following study, there is a significant downward regulation of BMP-2 and −5 in the scleral remodeling during myopia induction, especially BMP-2." (PMID 21403850, 2011). "In our study, BMP-2 was decreased in posterior sclera of myopia eyes, which would further indicate the BMP-2 is involved in the growth of human sclera." (PMID 21403850, 2011).